LINC02600 (long independently transcribed non-coding RNA 2600)
Synonyms: AC141928.1
Gene: Long non-coding RNA gene on chromosome 4 (3,758,748 to 3,763,390, reverse strand). Ensembl gene ENSG00000250986.
Diseases named in the same sentence as LINC02600 in open-access papers:
LINC02600 is named in the same sentence as 1 disease in open-access papers, as found by Europe PMC text mining. Sharing a sentence is not in itself a finding about the gene and the disease.
LINC02600 shares sentences with these, for which no sentence is quoted: cancer (1 paper).